AHR (aryl hydrocarbon receptor)
Diseases named in the same sentence as AHR in open-access papers (continued):
Sharing a sentence is not in itself a finding about the gene and the disease.
psychosis (2 papers, 2024). "Aberrant AhR overactivation has been associated with psychosis, while several antagonists of this receptor exert antipsychotic properties." (PMID 38892092, 2024). "At the molecular level, AhR is the equivalent of VENs, as this protein responds to both endogenous and exogenous ligands, including lipid peroxides and other insomnia and psychosis-related molecules." (PMID 38541916, 2024). "Aberrantly activated AhR, the master regulator of cellular senescence, explains not only how gut microbes and/or their molecules trigger psychosis but also how environmental pollutants precipitate SCZ or SLDs." (PMID 38892092, 2024).
retinal diseases (2 papers, 2017 to 2018). "Interestingly, several recent reports have demonstrated that loss of AHR caused development of retinal degenerative diseases similar to the retinal diseases caused by NR2E3 depletion." (PMID 28878246, 2017).
retinal ischemia (2 papers, 2023 to 2026). A ischemic disease that involves the retina. "Activation of AhR has anti-inflammatory effects; and this has been shown in animal models of human disease, such as autoimmune encephalomyelitis and retinal ischemia/reperfusion injury." (PMID 41534303, 2026).
retinitis pigmentosa (2 papers, 2021). Retinitis pigmentosa (RP) is an inherited retinal dystrophy leading to progressive loss of the photoreceptors and retinal pigment epithelium and resulting in blindness usually after several decades. "The function of AHR in the retina, particularly in RPE cells, has attracted attention as it is known that splicing mutations in AHR are associated with retinitis pigmentosa." (PMID 34698116, 2021).
seborrheic dermatitis (2 papers, 2022 to 2025). A chronic, inflammatory skin disorder that affects the scalp, central face and skin folds; it is characterized by scaling and itching. "Patients with seborrheic dermatitis (SD), a Malesezzia associated skin disease, were found to have in their skin extracts a 10–1000-fold higher capacity for AhR activation compared to control." (PMID 35458697, 2022). "Interestingly, 6-formylindolo[3,2-b]carbazole (6-FICZ), one of the most active AhR inducers and amongst the proposed receptor’s endogenous ligands, has been detected in Malassezia furfur isolates from lesional skin, as well as in skin scales from patients with seborrhoeic dermatitis." (PMID 39942795, 2025).
severe acute respiratory syndrome (2 papers, 2020 to 2021). A viral respiratory infection caused by the SARS coronavirus. "Recent work on the pathophysiology of the severe acute respiratory syndrome-coronavirus (SARS-CoV)-2 in the COVID-19 pandemic has highlighted the co-ordinating role of the aryl hydrocarbon receptor (AhR), including in the suppression of CD8+ T cell and natural killer (NK) cell cytotoxicity." (PMID 33375613, 2020).
Shock (2 papers, 2019). The state in which profound and widespread reduction of effective tissue perfusion leads first to reversible, and then if prolonged, to irreversible cellular injury. "In addition, in the absence of AhR in macrophages, mice are more susceptible to LPS-induced endotoxic shock and present with an increase in pro-inflammatory IL-6 expression." (PMID 31722204, 2019).
Sjögren’s syndrome (2 papers, 2024). "A recent study showed that the defective AhR activation led to impaired regulation of polymorphonuclear (PMN) MDSCs in a mouse model of experimental Sjögren’s syndrome (ESS)." (PMID 39211042, 2024). "PMN-MDSCs from NOD mice and mice model of primary Sjögren’s syndrome expressed low levels of AhR in consistence with reduced immunosuppressive capacity and impaired ability to produce ROS." (PMID 38495880, 2024). "Moreover, AhR antagonist treatments or tryptophan-free diet in mice model of primary Sjögren’s syndrome showed similar effects to that observed with Anti-Ly6G treatment exacerbating development of the disease." (PMID 38495880, 2024).
skin infection (2 papers, 2014 to 2024). An inflammatory process affecting the skin, caused by bacteria, viruses, parasites, or fungi. "When skin extracts are isolated from patients with ongoing skin infection, AhR is potently activated, and an increased concentration of AhR ligands in the skin has been linked to the development of Malassezia-associated skin diseases." (PMID 25566253, 2014).
skin pigmentation disorder (2 papers, 2021 to 2022). A pigmentation disease that involves the zone of skin. "Previous studies confirmed at least a partial role of AhR in the pathogenesis of various skin diseases, including inflammatory diseases, skin pigmentation disorders, and cancer." (PMID 33499346, 2021).
Streptococcus pneumoniae infection (2 papers, 2022). "After Streptococcus pneumoniae infection, the accumulation of eosinophils in the bronchoalveolar lavage fluid (BALF) and blood, the release of Th2 cytokines from the mediastinal lymph nodes, spleen cells, and aryl hydrocarbon receptor (AHR) was observed." (PMID 35911120, 2022).
testicular germ cell tumor (2 papers, 2020 to 2023). A germ cell tumor arising from the testis. "Remarkably, they have also found a positive correlation between AhR expression and immune stimulators including TMEM173 and TNF superfamily member 13 (TNFSF13) in testicular germ cell tumors as well as CD48 and TNFRSF25 in uveal melanoma." (PMID 37241719, 2023). "Furthermore, recent data indicates a correlation between AhR expression and immune inhibitors including colony-stimulating factor 1 receptor (CSF1R) and galectin 9 (LGALS9) in uterine carcinosarcoma and IL10RB in testicular germ cell tumors." (PMID 37241719, 2023).
Thrombocytosis (2 papers, 2023 to 2025). Increased numbers of platelets in the peripheral blood. "Based on these lines of information, we hypothesized that in individuals with cancer, Kyn is mobilized to trigger thrombocytosis and erythrocytopenia by activating AhR." (PMID 37919525, 2023). "Together, these results suggest that increased AhR activity may unbalance the differentiation of MEPs into MkPs and EryPs, thus leading to thrombocytosis and erythropenia in tumor-bearing hosts." (PMID 37919525, 2023).
thymic lymphoma (2 papers, 2023).
thyroid (2 papers, 2015 to 2020). "After having validated the system, to better understand the functions of AhR in thyroid carcinogenesis, we evaluated the transcriptional effects of kynurenine-mediated activation of the receptor on genes involved in immune-tolerance and EMT." (PMID 31936153, 2020). "Clinical meta data associated to expression profiles were further analyzed to assess if AHR transcription expression may be a function of thyroid disease progression or histotype." (PMID 26392334, 2015).
uveitis (2 papers, 2018 to 2023). An inflammatory process affecting a part of or the entire uvea. "Aryl hydrocarbon receptor (AhR), a ligand-activated nuclear receptor, has been implicated to play a role in human uveitis, although the exact mechanisms remain poorly understood." (PMID 30090104, 2018). "We expanded these observations and provided further details concerning the inhibition of uveitis by AhR activation." (PMID 30090104, 2018). "Following EAU induction, AhR−/− mice had more severe clinical and histopathological manifestations of uveitis than AhR+/+ mice." (PMID 30090104, 2018). "Our study is the first to analyze the role of AhR in BRB breakdown which is a prominent feature of uveitis." (PMID 30090104, 2018). "Moreover, activating the aryl hydrocarbon receptor (AHR) and its involved signals is associated with the protection of RPE cells and the retina, as well as the inhibition of choroidal neovascularization, uveitis, and AMD." (PMID 37817192, 2023). "After immunization with IRBP651–670, AhR+/+ mice showed obvious histopathological signs of uveitis compared with non-immunized mice, as evidenced by the retinal folding, photoreceptor damage, and infiltration of inflammatory cells throughout the retina and choroid." (PMID 30090104, 2018).
acute graft vs. host disease (1 paper, 2018). Graft-versus-host disease (GVHD) is a common complication following an allogeneic tissue transplant. "Additionally, the expression of AHR on T cells was shown to be critical in blocking the generation of peripheral Tregs in the lower gastrointestinal tract after a bone marrow transplant, suggesting the AHR on donor T cells is essential for pathogenesis in acute graft vs. host disease." (PMID 30574142, 2018).
Acute hepatitis (1 paper, 2016). Acute hepatic injury resulting from inflammation typically accompanied by increased serum alanine transaminase activity. "Notch signaling enhanced IL-22 production by CD4+ T cells even in absence of STAT3 by stimulation of AhR in a ConA-mediated acute hepatitis model in RBP-J−/− mice." (PMID 27800305, 2016).
acute lung injury (1 paper, 2026). A condition of lung damage that is characterized by bilateral pulmonary infiltrates (pulmonary edema) rich in neutrophils, and in the absence of clinical heart failure. "The in vivo results showed that oral IMP activated the AHR/ALDH3A1 and Nrf2/HO-1/GPX4 pathways in lung tissue, thus improving lung dysfunction and inflammation in acute lung injury (ALI) mice induced by LPS." (PMID 41513604, 2026).
Adrenal insufficiency (1 paper, 2022). Insufficient production of steroid hormones (primarily cortisol) by the adrenal glands. "In follow-up within 1-year, stratified analyses showed that female COP patients had a higher risk for adrenal insufficiency than female references, with an AHR of 23.8 (95% CI: 3.2–177.1)." (PMID 36171402, 2022).
alcohol abuse (1 paper, 2024). The use of alcoholic beverages to excess, either on individual occasions ("binge drinking") or as a regular practice. "Dysbiosis of the gut microbiota, often exacerbated by factors like alcohol abuse, can lead to increased production of metabolites that excessively activate the AhR, potentially exacerbating CNS inflammation." (PMID 39290562, 2024).
Apnea (1 paper, 2021). Lack of breathing with no movement of the respiratory muscles and no exchange of air in the lungs. "Results of multivariable logistic regression analysis to examine the effects of AHR and CLOCK gene polymorphisms on caffeine therapy in apnea-free group and apneic preterm infants." (PMID 35145399, 2021).
bacterial pneumonia (1 paper, 2023). Acute infection of the lung parenchyma caused by bacteria (e.g., Streptococcus pneumoniae, Haemophilus influenzae, Chlamydia pneumoniae, Mycoplasma pneumoniae, and Legionella pneumophila). "Together this data suggests that alcohol disrupts NK cell specific TGF-β1 and AhR signaling pathways leading to decreased pulmonary recruitment and cytolytic activity thereby increasing susceptibility to alcohol-associated bacterial pneumonia." (PMID 37886455, 2023). "To further validate the role of TGF-b1 and AhR signaling in host defense against alcohol-associated bacterial pneumonia we repeated the previous experimental paradigm with several additional control groups." (PMID 37886455, 2023). "Together this data suggests that alcohol disrupts NK cell specific TGF-β and AhR signaling pathways leading to decreased pulmonary recruitment and cytolytic activity thereby increasing susceptibility to alcohol-associated bacterial pneumonia." (PMID 37886455, 2023). "Together this data suggests that alcohol causes disruption of NK cell-specific TGF-β and AhR signaling leading to decreased pulmonary recruitment and cytolytic activity thereby increasing susceptibility to alcohol-associated bacterial pneumonia." (PMID 37886455, 2023). "This study focused on the intestinal microbiota from alcohol consuming mice to understand the relationship between alcohol, the microbiota, TGF-b and AhR signaling in NK cells, and host defense against bacterial pneumonia." (PMID 37886455, 2023).
Behçet’s disease (1 paper, 2022). "Additionally, gene expression of the AHR is decreased in PBMCs isolated from Behçet’s disease patients compared with control." (PMID 35295218, 2022). "AHR activation may also be useful in treating Behçet’s disease." (PMID 35295218, 2022).
benign meningioma (1 paper, 2023). A grade I, slowly growing meningioma. "Overall, our findings suggest that in intracranial benign meningioma, genes of the AhR signaling pathway are involved in the adaptation to hypoxia in both HIF-1α-dependent and HIF-1α-independent manners." (PMID 37305351, 2023). "The primary cultured cells from benign meningiomas in our study showed responses to the hypoxia mimetic (in terms of mRNA expression of AhR, ARNT, and an AhR target gene) that differ from those described in the literature; this discrepancy may be due to differences between the analyzed tissues." (PMID 37305351, 2023).
Blindness (1 paper, 2011). Blindness is the condition of lacking visual perception defined as a profound reduction in visual perception. "We anticipate that manipulating AhR signaling, preferable with non-toxic ligands, could represent a useful approach to control an important cause of human blindness." (PMID 22174686, 2011).
blood disease (1 paper, 2018). A disease that occurs in the blood. "For example, exposure to environmental toxicants which activate the aryl hydrocarbon receptor (AHR) have been linked to blood diseases in humans." (PMID 30388136, 2018). "In addition, numerous studies have suggested a role for AHR in both regulation of hematopoietic cells, and in the development of blood diseases." (PMID 30388136, 2018).
brain cancer (1 paper, 2020). A primary or metastatic malignant neoplasm affecting the brain. "The involvement of AhR in brain cancer is complicated, depending on the type of cancer, on ligands that activate AhR, and other features of the pathological process." (PMID 32325928, 2020).
brain infarction (1 paper, 2019). Tissue necrosis in any area of the brain, including the cerebral hemispheres, the cerebellum, and the brain stem. "The aryl hydrocarbon receptor (AHR) antagonist 6,2′,4′-trimethoxyflavone (TMF)-treated wild-type (WT) and AHR conditional knockout (AHRcKO) mice exhibited a reduction in brain infarction compared with the vehicle-treated WT and AHRflx/flx mice, respectively." (PMID 31606043, 2019).
Calcium oxalate nephrolithiasis (1 paper, 2025). The presence of calcium- and oxalate-containing calculi (stones) in the kidneys. "In a calcium oxalate nephrolithiasis model, IAA ameliorated oxidative stress and inflammation via AhR activation and NF-κB suppression." (PMID 41373425, 2025).
Chagas cardiomyopathy (1 paper, 2023). A disease of the cardiac muscle developed subsequent to the initial protozoan infection by trypanosoma cruzi. "Given the persistent cardiac inflammation observed in Chagas cardiomyopathy (CCC) patients, we hypothesized that it could potentially influence the levels of AhR agonists in the serum." (PMID 38283348, 2023).
chloracne (1 paper, 2014). ACNE-like skin eruptions caused by exposure to CHLORINE-containing compounds. "Mechanistic studies showed that the TCDD-induced chloracne-like phenotype depends on AhR activation whereas AhR knock down did not appear sufficient to induce the phenotype." (PMID 24161567, 2014). "However, nowadays TCDD-induced chloracne is extremely rare and in recent case studies, exposure to a “cocktail” of compounds hinders interpretation of the pathophysiological role of TCDD and AhR activation." (PMID 24161567, 2014).
chronic graft versus host disease (1 paper, 2023). Chronic graft versus host disease (GVHD) is a complication that can occur after a stem cell or bone marrow transplant in which the newly transplanted donor cells attack the transplant recipient's body. "Targeting AHR or IL-22RA1 had a significant impact on the pathogenesis of murine chronic graft-versus-host disease (cGVHD), an autoimmune-like complication following allo-HCT13." (PMID 37938575, 2023). "Furthermore, targeting AHR or IL-22RA1 has significant impacts on severity of murine chronic graft-versus-host disease (cGVHD), which is an autoimmune-like complication following allogeneic hematopoietic cell transplantation." (PMID 37938575, 2023).
Clear Cell Ovarian Cancer (1 paper, 2019). "AhR expression was detected in all histological subtypes, with clear cell ovarian cancer displaying the highest staining intensity." (PMID 31212758, 2019). "In our study, the highest AhR levels were seen in clear cell ovarian cancer patients." (PMID 31212758, 2019). "Further understanding of the AhR pathway, especially in clear cell ovarian cancer, might open up new therapeutic approaches for this rare histologic subtype." (PMID 31212758, 2019).
Cryptosporidium infection (1 paper, 2024). "AHR-deficient mice, as well as mice fed purified diet deprived of AHR ligands, were highly susceptible to Cryptosporidium infection due to the reduction in IELs which depend on AHR signalling for survival and are essential to control the infection." (PMID 39242971, 2024).
demyelination (1 paper, 2023). "Taken together, these data suggest that AhR is important in regulating remyelination following cuprizone-induced demyelination." (PMID 36966295, 2023).
diabetic cardiomyopathy (1 paper, 2022). Diabetic cardiomyopathy is a disorder of the heart muscle in people with diabetes. "However, LncRNA GAS5 inhibits NLRP3 (inflammasome) activation-mediated pyroptosis in diabetic cardiomyopathy by targeting miR-34b-3p/AHR." (PMID 36061542, 2022). "GAS5 acts as a competing endogenous RNA to enhance AHR expression by sponging miR-34b-3p and repressing NLRP3 (inflammasome) activation-mediated pyroptosis to improve diabetic cardiomyopathy." (PMID 36061542, 2022).
Duchenne muscular dystrophy (1 paper, 2020). Duchenne muscular dystrophy (DMD) is a neuromuscular disease characterized by rapidly progressive muscle weakness and wasting due to degeneration of skeletal, smooth and cardiac muscle. "The identification and verification of AhR as a target for ezutromid represents the first validation of a disease‐modifying drug target in Duchenne muscular dystrophy." (PMID 31755636, 2020). "Chemical proteomics and phenotypic profiling illustrate the aryl hydrocarbon receptor (AhR) is a target of ezutromid, the first‐in‐class utrophin modulator for the treatment of Duchenne muscular dystrophy." (PMID 31755636, 2020).
endometrial adenocarcinoma (1 paper, 2017). "In the endometrial adenocarcinoma Ishikawa cells, PCBs affected the expression of inflammatory factors through estrogen receptors (ERs) and the aryl hydrocarbon receptor (AhR), with no adverse effects on estrogen metabolism." (PMID 28315012, 2017).
endometrioid adenocarcinoma (1 paper, 2024). An adenocarcinoma characterized by the presence of malignant glandular epithelial cells resembling endometrial cells. "Moreover, the expression of AHR was found to be higher in oestrogen-independent responsive grade 3 endometrioid adenocarcinomas than in oestrogen-dependent responsive grade 1 and 3 endometrioid adenocarcinomas." (PMID 38539419, 2024).
enterocolitis (1 paper, 2023). An inflammatory process affecting the small intestine and colon. "It is also found that downregulation of CYP1A2 is observed during inflammation, whereas AhR activation protects intestinal epithelium from enterocolitis by promoting CYP1A2 expression, and that indole derivatives activate AhR to promote IL-22 secretion, which boosts intestinal mucosal defense." (PMID 37344888, 2023).
epidermal cysts (1 paper, 2014). "The important role of AHR in MADISH pathogenesis is supported by the finding that transgenic mice expressing a constitutively active mutant of the Ahr receptor (caAhr) in keratinocytes also develop epidermal cysts." (PMID 24503019, 2014).
esophageal tumors (1 paper, 2019). "The overexpression of AhR has been described in various cancers including pancreatic, prostate, lung, urinary tract, and esophageal tumors." (PMID 31212758, 2019).